SEL1L2 (SEL1L2 adaptor subunit of SYVN1 ubiquitin ligase)
Synonyms: Sel-1L2; C20orf50; DKFZp434C1826
Tractability: Antibody: UniProt predicts a signal peptide or a membrane-spanning region. PROTAC: ubiquitination databases record sites on it.
Gene: Protein-coding gene on chromosome 20 (13,849,247 to 13,996,443, reverse strand). Ensembl gene ENSG00000101251.
Subcellular location: Membrane; Cell projection, cilium; Nucleus speckle
Gene Ontology:
Biological process: ERAD pathway
Cellular component: cilium; nuclear speck; endoplasmic reticulum membrane; membrane
Genetic constraint (gnomAD): Loss-of-function variants: 39 observed, 52.06 expected, observed/expected ratio (o/e) 0.75, 90% interval 0.58 to 0.98. The upper end of that interval is the gene's LOEUF score, 0.98, which puts it in group 4 of 6, group 1 being the genes least tolerant of losing a copy. Missense variants: 478 observed, 501.9 expected, observed/expected ratio (o/e) 0.95, 90% interval 0.88 to 1.03. Synonymous variants: 165 observed, 175.91 expected, observed/expected ratio (o/e) 0.94, 90% interval 0.83 to 1.07.
Homologues: Orthologues: chimpanzee SEL1L2 (99% identical), macaque SEL1L2 (96% identical), rabbit SEL1L2 (89% identical), pig SEL1L2 (89% identical), rat Sel1l2 (86% identical), mouse Sel1l2 (86% identical), guinea pig SEL1L2 (85% identical), Caenorhabditis elegans sel-1 (35% identical). Paralogues in human: SEL1L (48% identical), SEL1L3 (23% identical), LRP2BP (10% identical), DELE1 (10% identical).
Diseases named in the same sentence as SEL1L2 in open-access papers:
SEL1L2 is named in the same sentence as 4 diseases in open-access papers, as found by Europe PMC text mining. Sharing a sentence is not in itself a finding about the gene and the disease.
SEL1L2 shares sentences with these, for which no sentence is quoted: Cranial meningocele (1 paper); Obesity (1); partial epilepsy (1); trigonocephaly (1).